ALDH2 (aldehyde dehydrogenase 2 family member)
Diseases named in the same sentence as ALDH2 in open-access papers (continued):
Sharing a sentence is not in itself a finding about the gene and the disease.
diabetes (continued). "Previous studies also indicated that, with the development of diabetes, cardiac ALDH2 activity was further decreased, and inhibition of ALDH2 by oxidative stress leads to cardiac dysfunction in diabetes mellitus." (PMID 27829984, 2016). "In previous study, we observed that, with the progression of diabetes, myocardial ALDH2 expression was further decreased accompanying decreased ventricular function, and activation of ALDH2 can decrease diabetes- induced myocardial injury." (PMID 27829984, 2016). "We investigated the impact of genetically determined ALDH2 activity on diabetic microvascular and macrovascular complications in relation to drinking habits in Japanese patients with type 2 diabetes mellitus." (PMID 26599441, 2015). "It is conceivable that the associations between cardiovascular risk factors including lipid profile, BMI, and diabetes and the ADH1B and ALDH2 genotypes in Japanese alcoholics modify their risk of cardiovascular events." (PMID 26284938, 2015). "Further studies will be required to investigate the contrasting effects of genetically determined ALDH2 activity on microvascular and macrovascular complications in patients with type 2 diabetes mellitus." (PMID 26599441, 2015). "Treatment with EtOH at low concentration can decrease diabetes induced lung injury through activating ALDH2 expression." (PMID 25019090, 2014). "In conclusion, our results indicated that, in diabetes induced lung injury in rat model, pulmonary ALDH2 expression was decreased." (PMID 25019090, 2014). "EtOH at low concentration decreased diabetes induced lung injury through activating ALDH2 expression." (PMID 25019090, 2014). "Significant interactions were observed between alcohol and ADH1b (rs1229984) with respect to LDL and between alcohol and ALDH2 (rs886205) with respect to IGT/diabetes." (PMID 20700531, 2010). "This notion is further supported by studies in diabetes-related heart models, where ALDH2 activation has been shown to improve cardiac function and attenuate cardiomyocyte death, both in vivo and under high glucose conditions in vitro, without affecting systemic glucose levels." (PMID 40564981, 2025). "Previous studies suggested that ALDH2 dysfunction may contribute to a variety of human diseases including cardiovascular diseases, diabetes, neurodegenerative diseases, stroke, and cancer." (PMID 39905472, 2025). "We found that the myocardial ALDH2 activity was significantly reduced in vehicle- treated ALDH2*2 mice with diabetes-associated HFpEF relative to non-diabetic control mice." (PMID 36142350, 2022). "We found that vehicle-treated ALDH2*2 mice with diabetes-associated HFpEF ran shorter distances and duration until exhaustion compared to non-diabetic control ALDH2*2 mice." (PMID 36142350, 2022). "We found a significant increase in colocalization of LKB1 and 4HNE in the hearts of vehicle-treated ALDH2*2 mice with diabetes-associated HFpEF compared to the non-diabetic controls, implicating increased 4HNE adduction on LKB1." (PMID 36142350, 2022). "During disease progression of diabetes, ALDH2 activity reduced while the 4-HNE level increased." (PMID 33805825, 2021). "Acetaldehyde dehydrogenase 2 (ALDH2), a major enzyme involved in aldehyde detoxification, has been demonstrated to be beneficial for a growing number of human diseases, such as cardiovascular dysfunction, diabetes mellitus and neurodegeneration." (PMID 32070320, 2020). "Furthermore, our results indicated that ALDH2*2 carriers were at an increased risk of ISR, especially among those with diabetes." (PMID 31345174, 2019). "Of the non-ISR patients with diabetes, 54 (81.8%) carried the ALDH2*1/*1 allele, 11 (16.7%) carried the ALDH2*1/*2 allele, and 1 (1.5%) carried the ALDH2*2/*2 allele." (PMID 31345174, 2019). "Differences in ALDH2 expression may contribute to a wide variety of human diseases, including cardiovascular disease, diabetes, and cancer." (PMID 30245369, 2018).
diabetes (continued). "On the other hand, ALDH2*2 genotype seemed to be a risk factor for non-insulin-dependent diabetes mellitus in women, but not in men." (PMID 29552329, 2018). "Importantly, diabetes resulted in ALDH2 oxidation and decreased its activity whereas ischemia preconditioning by ethanol or PKC agonist induced ALDH2 phosphorylation and increased its activity." (PMID 28038474, 2017). "With the development of diabetes, ALDH2 mRNA were further decreased in DM8W groups (P < 0.01)." (PMID 27547765, 2016). "However, there are few researches on the relationship of myocardial ALDH2 and diabetes myocardial ischemia/reperfusion injury." (PMID 27829984, 2016). "When diabetes rats were pretreated with low concentration of EtOH, which was used as a tool to induce ALDH2 activity, LDH level was decreased; whereas LVDP, ±dp/dtmax, RP, SOD activity and Bcl-2 mRNA level were increased, MDA content and Bax mRNA level were decreased." (PMID 27829984, 2016). "To verify whether cardiac ALDH2 directly participates in diabetes-induced cardiomyocyte injury, in this study, we also applied high glucose induced cardiomyocyte injury to mimic diabetes." (PMID 27829984, 2016). "Thus, we designed the present study to investigate the impact of genetically determined ALDH2 activity on diabetic microvascular and macrovascular complications in relation to drinking habits in Japanese patients with type 2 diabetes mellitus." (PMID 26599441, 2015). "More recently it has been shown that ALDH-2 plays an important role for the reduction of myocardial damage during ischemia/reperfusion by reducing the infarct size and conferring cardio-protection in an experimental diabetes/MI model." (PMID 25402275, 2014). "But few reports focus on the relationship of pulmonary ALDH2 and diabetes induced lung injury." (PMID 25019090, 2014). "But it remains unknown whether activation of ALDH2 expression can prevent diabetes induced lung injury." (PMID 25019090, 2014). "Importantly, our findings demonstrate that regardless of the underlying mechanisms, the diabetes risk associated with ALDH2 variants can be effectively mitigated through lifestyle modifications, particularly weight management and WC control." (PMID 40046877, 2025). "In another study, ALDH2 overexpression in heart cells exposed to high glucose improved survival rates, decreased harmful molecule accumulation, and reduced inflammation-related proteins, suggesting a potential treatment strategy against diabetes-induced cardiac damage." (PMID 40564981, 2025). "As the field moves towards precision therapies addressing the endothelial–metabolic axis, ALDH2 gene therapy in CVECs offers a promising, translationally relevant strategy to counteract HFpEF progression, particularly in metabolically compromised patients burdened by obesity and diabetes." (PMID 40723901, 2025). "Combined treatment of EMP + Alda-1 ameliorated the hallmarks of diabetes-associated HFpEF, such as cardiac diastolic function and exercise capacity as well as decreased cardiomyocyte hypertrophy and myocardial fibrosis, more than the individual treatment with EMP in ALDH2*2 mice." (PMID 36142350, 2022). "We have experimental data confirming the important role of ALDH-2 in reducing the area of myocardial infarction during induced ischaemia/reperfusion along with data confirming its cardio-protective effect during experimentally induced myocardial infarction in diabetes." (PMID 33150520, 2021). "Indeed, we previously reported that diabetes-induced hyperglycemia led to generation of ROS, which could directly inhibit ALDH2 activity." (PMID 28038474, 2017). "Thus far, there have been no reports about the changes of ALDH2 in diabetes myocardial I/R injury, and the underlying cellular mechanisms are not clear." (PMID 27829984, 2016). "Therefore, in the present study, we firstly sought to determine whether ALDH2 expression also changed in diabetes myocardial I/R injury model." (PMID 27829984, 2016).
diabetes (continued). "Since diabetes induced lung injury accompanied with oxidative stress, while increasing ALDH2 expression could decrease oxidative stress, so we investigated whether activating pulmonary ALDH2 expression by EtOH could decrease lung oxidative stress injury in diabetic rats." (PMID 25019090, 2014). "Notably, alcohol consumption neither modified nor mediated the ALDH2–diabetes association." (PMID 40046877, 2025). "An interaction effect was also observed between ALDH2 (rs886205) and IGT/diabetes in the current study." (PMID 20700531, 2010). "Additional analyses revealed that insulin resistance (HOMA-IR), but not beta-cell function (HOMA-β), significantly mediated the ALDH2–diabetes relationship." (PMID 40046877, 2025). "Human studies have established a strong association between the ALDH2*2 variant and an increased risk of CAD, heart failure, and diabetes, regardless of alcohol consumption." (PMID 40564981, 2025). "Além disso, os níveis proteicos de ALDH2 e PI3K e AKT fosforilados foram marcadamente menores no grupo com diabetes do que no grupo controle, sendo revertidos no grupo tratado com orientina (Figura 3B-C)." (PMID 40834212, 2025). "Human studies have established a strong association between the ALDH2*2 variant and increased risk of CAD, heart failure, and diabetes, regardless of alcohol consumption." (PMID 40564981, 2025). "Of the ISR patients who did not have diabetes, equal proportions of ALDH2*1/*1, ALDH2*1/*2 and ALDH2*2/*2 were 88 (65.7%), 39 (29.1%), and 7 (5.2%), respectively." (PMID 31345174, 2019). "The present study identified a possible impact of ALDH2 activity on myocardial infarction in patients with type 2 diabetes mellitus, irrespective of alcohol consumption." (PMID 26599441, 2015). "Moreover, a significant interaction effect was observed between ALDH2 (rs886205) and IGT/diabetes in the adjusted model." (PMID 20700531, 2010). "The relationship of this ALDH2 variant as well as the ADH7 and ALDH1b1 variants with diabetes and CHD related phenotypes have not been studied previously, except from a previous study (n = 1,216) from our group." (PMID 20700531, 2010). "Similarly we speculate that the hyperglycemic stress in ALDH2∗2 carriers with diabetes or noncarriers with other comorbidities with low ALDH2 activity may be vulnerable to cardiac tissue damage." (PMID 27882330, 2016). "However, increasing alcohol consumption may not be recommended in ALDH2 *2 carriers with type 2 diabetes mellitus, because accumulated acetaldehyde is known to be a significant carcinogen in humans." (PMID 26599441, 2015).
myocardial infarction (49 papers, 2010 to 2026). Gross necrosis of the myocardium, as a result of interruption of the blood supply to the area, as in coronary thrombosis. "Recent research highlights that men with the ALDH2*2 variant are at greater risk of severe heart damage during heart attacks, underscoring the need for personalized medical interventions in East Asian populations with this variant." (PMID 40564981, 2025). "ALDH2 deficiency enlarged myocardial infarct size, increased CK-MB, LDH and 4-HNE; iron accumulation; MDA production; glutathione depletion; GPX4 inactivation; increased ACSL4 and TfR1; downregulated FTH1and GPX4." (PMID 37942067, 2023). "The variant of ALDH2 was thought to be associated with Acute Myocardial Infarction (AMI) due to the consumption of alcohol." (PMID 35787671, 2022). "Studies have found that the ALDH2 GG type is one of the risk factors for the incidence of myocardial infarction in Japanese men." (PMID 36229771, 2022). "The association of the ALDH2 *2 allele with myocardial infarction has been reported in Japanese, Koreans and Chinese populations." (PMID 26599441, 2015). "Downregulation of ALDH2 was evidenced after myocardial infarction and the underlying mechanism is not fully understood." (PMID 25629048, 2015). "In summary, the present study suggests DNA methylation has an effect on the upstream sequence of ALDH2 promoter, which is possibly associated with the decrease of ALDH2 expression after myocardial infarction." (PMID 25629048, 2015). "It has been suggested that the risk of coronary heart disease and myocardial infarction may be increased due to the Glu504Lys variant in the ALDH2 gene, which is responsible for reducing the ability of ALDH2 to metabolize acetaldehyde." (PMID 36289612, 2022). "It is reasonable to speculate that in human, ALDH2*2 with reduced enzymatic function will promote the formation of atherosclerosis, which is the underlying cause of acute myocardial infarction." (PMID 35787671, 2022). "Also it demonstrated that the ALDH2*2 genotype is a risk factor for myocardial infarction in Japanese men." (PMID 29552329, 2018). "C12orf51 transcript on 12q24 and has been reported to be in high linkage disequilibrium with SNPs in ALDH2 and ALDH2 was reported to be associated with cardiomyocyte apoptosis post myocardial infarction induced by microRNA-34A, and H2O2-induced apoptosis in peripheral blood mononuclear cells." (PMID 25008389, 2014). "Our study demonstrates that DNA methylation might contribute to the upstream regulation of ALDH2 after myocardial infarction, suggesting that there is an association between ALDH2 promoter hypermethylation and myocardial infarction (The location of ALDH2 in Rattus norvegicus is 12q16." (PMID 25629048, 2015). "For the cardioprotective effects, accumulating evidence confirms that ALDH2 activation mitigates cardiac injury across multiple pathological contexts: acute myocardial infarction, coronary artery disease, and myocardial ischemia–reperfusion injury." (PMID 41542286, 2026). "Former studies indicated that HSPA8 can interact with aldehyde dehydrogenase 2 (ALDH2) to regulate fibroblast senescence after oxygen–glucose deprivation, providing an option to effectively intervene in fibroblast senescence after myocardial infarction." (PMID 40538098, 2025). "Many clinical studies have shown that individuals with ALDH2 deficiency are more prone to cardiovascular complications, including CAD, myocardial infarction, and heart failure." (PMID 40564981, 2025). "Alda-1, a selective ALDH2 activator, decreases lipid peroxidation and myocardial apoptosis, leading to improved cardiac function post-myocardial infarction and reduced fibrosis in heart failure models." (PMID 40564981, 2025). "Three reports of experimental myocardial infarction and stroke as well as human materials implicate ALDH2 or Hsp70 in cell death." (PMID 37693644, 2023).
myocardial infarction (continued). "A risk nomogram was established by ACSL1, ALDH2, CYP27A1 and PPARA, demonstrating a good ability for DCM and myocardial infarction prediction." (PMID 37056578, 2023). "Multiple studies have indicated that increasing ALDH2 expression alleviates AP, myocardial infarction, atherosclerosis, heart failure, and ALI by inhibiting apoptosis." (PMID 36820405, 2023). "Prior research has established that activating ALDH2 can effectively aid in repairing myocardial infarction injuries, specifically in the maintenance of mitochondrial homeostasis." (PMID 38247467, 2023). "Both myocardial infarction and acute stroke in rats are the case of acute, intense ischemia of the heart or the brain inducing a similar pattern of ALDH2 downregulation." (PMID 37693644, 2023). "It is known that after myocardial infarction, the co-administration of nitroglycerin and Alda-1—an activator of ALDH2—has positive effects on the metabolism of reactive aldehyde adducts by reducing the cardiac dysfunction generated by the use of nitroglycerin." (PMID 36555095, 2022). "ALDH2 has shown to play a protective role in myocardial infarction via modulating the β-catenin/Wnt signaling." (PMID 36923554, 2022). "ALDH2 is considered a cardioprotective enzyme that is capable of both preventing the onset of ischemic damage (during myocardial infarction) and also in reducing the infarct area." (PMID 36555095, 2022). "Overexpression of ALDH2 in a mouse model or enhancement of its activity via the small-molecular activator Alda-1 diminished myocardial infarct size, prevented the progression of ventricular remodeling and improved the long-term survival after I/R." (PMID 34203800, 2021). "In the treatment of myocardial infarction, we have obtained key targets of Yixinyin, which are ALDH2, C5AR1, FOS, IL1B, TLR2, TXNRD1." (PMID 34799616, 2021). "FCN1, CD14, S100A9, ALDH2, hsa-let-7d, hsa-let-7b, hsa-miR-124-3, and hsa-miR-9-1 were identified as potential candidate regulators in acute myocardial infarction." (PMID 30886860, 2019). "Elevated ALDH2 is beneficial in reducing injury following myocardial infarction, stroke and other oxidative stress and aldehyde toxicity-related diseases." (PMID 28056995, 2017). "ALDH2 activator and ALDH2 overexpression attenuated infarct size in a rodent model of myocardial infarction." (PMID 26599441, 2015). "Three recent meta-analyses consistently supported a contributory role of ALDH2 rs671 polymorphism in susceptibility to CAD and myocardial infarction, with the rs671-A allele associating with an increased risk of at least 1.2 and 1.32." (PMID 25047496, 2014). "However, beyond alcohol sensitivity, the ALDH2*2 variant is associated with an increased risk of cardiovascular disease, including CAD, myocardial infarction, and heart failure." (PMID 40564981, 2025). "Research reveals that individuals carrying the ALDH2*2 variant have a higher risk of severe cardiovascular events, including myocardial infarction and macrovascular complications, regardless of alcohol intake." (PMID 40564981, 2025). "Enhancing ALDH2 activity through pharmacological means following a myocardial infarction may lead to an improvement in ischemic heart injury." (PMID 40287718, 2025). "In this study, bioinformatics analysis revealed that the signaling pathway for fibroblast senescence is significantly activated in mice after myocardial infarction (MI), and that ALDH2 might be a crucial molecule responsible for inducing this change." (PMID 38247467, 2023). "The pharmacological enhancement of ALDH2 activity after myocardial infarction could improve ischemic heart injury." (PMID 38247467, 2023). "The myocardial infarct size was limited in ALDH2-Tg group compared to the I/R group." (PMID 34660582, 2021). "In 2008, Science reported that ALDH2 can delay heart failure after myocardial infarction." (PMID 32626739, 2020).